RNU6-60P (RNA, U6 small nuclear 60, pseudogene)
Synonyms: RNU6-60
Gene: Small nuclear RNA gene on chromosome 13 (48,987,915 to 48,988,017, forward strand). Ensembl gene ENSG00000201662.
Homologues: Orthologues: chimpanzee U6 (95% identical), mouse Gm22290 (90% identical), dog U6 (83% identical), rat U6 (83% identical), pig U6 (82% identical), guinea pig U6 (66% identical). Paralogues in human: RNU6-12P (94% identical), RNU6-13P (94% identical), RNU6-32P (94% identical), RNU6-589P (94% identical), RNU6-1 (93% identical), RNU6-1011P (93% identical), RNU6-1316P (93% identical), RNU6-16P (93% identical), RNU6-17P (93% identical), RNU6-18P (93% identical), RNU6-2 (93% identical), RNU6-26P (93% identical), and 1284 more.